PHF20 (PHD finger protein 20)
Description:
Methyllysine-binding protein, component of the MOF histone acetyltransferase protein complex. Not required for maintaining the global histone H4 'Lys-16' acetylation (H4K16ac) levels or locus specific histone acetylation, but instead works downstream in transcriptional regulation of MOF target genes (By similarity). As part of the NSL complex it may be involved in acetylation of nucleosomal histone H4 on several lysine residues.
Synonyms: C20orf104; GLEA2; HCA58; NZF; TZP; dJ1121G12.1; TDRD20A
Tractability: PROTAC: UniProt records ubiquitination sites on it; ubiquitination databases record sites on it.
Gene: Protein-coding gene on chromosome 20 (35,771,968 to 35,950,385, forward strand). Ensembl gene ENSG00000025293.
Subcellular location: Nucleus
Subcellular location (Human Protein Atlas): Nucleoplasm; Cytosol; Golgi apparatus; Nuclear membrane
Pathways (Reactome):
Gene expression (Transcription): Formation of WDR5-containing histone-modifying complexes
Chromatin organization: HATs acetylate histones
Gene Ontology:
Molecular function: protein binding
Biological process: positive regulation of DNA-templated transcription; regulation of transcription by RNA polymerase II
Cellular component: histone acetyltransferase complex; MLL1 complex; NSL complex; nuclear membrane; nucleoplasm; nucleus
Genetic constraint (gnomAD): Loss-of-function variants: 15 observed, 92.94 expected, observed/expected ratio (o/e) 0.16, 90% interval 0.11 to 0.25. The upper end of that interval is the gene's LOEUF score, 0.25, which puts it in group 1 of 6, group 1 being the genes least tolerant of losing a copy. Missense variants: 842 observed, 1,135.1 expected, observed/expected ratio (o/e) 0.74, 90% interval 0.7 to 0.79. Synonymous variants: 398 observed, 435.48 expected, observed/expected ratio (o/e) 0.91, 90% interval 0.84 to 0.99.
Homologues: Orthologues: chimpanzee PHF20 (99% identical), macaque PHF20 (99% identical), dog PHF20 (94% identical), rabbit PHF20 (92% identical), guinea pig PHF20 (92% identical), pig PHF20 (90% identical), mouse Phf20 (89% identical), rat Phf20 (88% identical), tropical clawed frog phf20 (57% identical), zebrafish phf20b (40% identical), zebrafish phf20a (36% identical), Drosophila melanogaster MBD-R2 (17% identical). Paralogues in human: PHF20L1 (33% identical).
Diseases named in the same sentence as PHF20 in open-access papers:
PHF20 is named in the same sentence as 26 diseases in open-access papers, as found by Europe PMC text mining. Sharing a sentence is not in itself a finding about the gene and the disease. The quoted sentences say what the papers report.
glioblastoma (8 papers, 2008 to 2024). The most malignant astrocytic tumor (WHO grade IV). "Plant homeodomain finger protein 20 (PHF20) was highly expressed in primary human gliomas, and its expression was found to be associated with tumour grade, which relates to glioblastoma." (PMID 35057823, 2022). "Initially, PHF20 was identified as a tumour‐associated antigen that elicited an immune response in the serum of glioblastoma patients." (PMID 35979628, 2022). "Previous studies have shown that ING3 promotes prostate cancer growth by activating the androgen receptor, and PHF20 promotes glioblastoma cell malignancies through a WISP1/BGN‐Dependent pathway." (PMID 39538416, 2024). "One particular protein of interest in glioblastoma regulation is plant homeodomain finger protein 20 (PHF20)." (PMID 29033691, 2017). "Besides, PHF20 is highly expressed in primary human glioma specimens, and functions as an immunogenic antigen in glioblastoma." (PMID 29033691, 2017). "A total of 540 genes (175 up-regulated genes and 365 down-regulated genes) were differentially expressed following knockdown of PHF20, which suggests that PHF20 may be a key regulator in glioblastoma." (PMID 29033691, 2017). "Therefore, PHF20 might be a novel biomarker for early diagnosis, and a potential target for glioblastoma therapies." (PMID 29033691, 2017). "However, the molecular mechanism by which PHF20 regulates glioblastoma remains poorly understood." (PMID 29033691, 2017).
glioma (8 papers, 2008 to 2022). A benign or malignant brain and spinal cord tumor that arises from glial cells (astrocytes, oligodendrocytes, ependymal cells). "Intriguingly, it had also been reported that the expression level of PHF20 was significantly associated with the pathological grade of glioma." (PMID 33117706, 2020). "The expression of PHF20 is elevated in glioma samples and associated with potential poor prognosis in patients with glioma." (PMID 33117706, 2020). "Plant homeodomain finger protein 20 (PHF20) is highly expressed in primary human gliomas and its expression is associated with tumor grade." (PMID 29033691, 2017). "PHF20 was originally identified in glioma patients and is significantly associated with glioma pathological tumor grade." (PMID 29033691, 2017). "PHF20 expression levels have also been associated with the pathological tumor grade of gliomas." (PMID 29033691, 2017). "However, the underlying molecular pathways regulated by PHF20 in glioma remain largely undetermined." (PMID 29033691, 2017). "WDR5 is a well-known chaperone of PHF20 and has been reported to function as an oncogene in many cancers, including glioma." (PMID 33117706, 2020). "Plant homeodomain-finger containing protein 20 (PHF20) has been previously identified as a novel antigen in glioma patients and named as glioma-expressed antigen 2 (GLEA2)." (PMID 33117706, 2020). "We showed a marked increase of PHF20 expression in both the cytoplasm and nucleus of the glioma samples compared to the normal brain tissues." (PMID 33117706, 2020). "To determine PHF20 expression in glioma, we firstly measured the expression of PHF20 in glioma tissues by IHC staining." (PMID 33117706, 2020). "Overall, this study indicated that PHF20 is a pivotal upstream gene that influences the occurrence and development of glioma by regulating a series of tumor-related genes, like FEN1, CCL3, PLCB1, NRAS and PIK3s, and involved in apoptosis signaling pathways." (PMID 29033691, 2017). "The relative expression level of PHF20 in U87 cells was higher than in other glioma cell lines (p < 0.05)." (PMID 29033691, 2017). "Expression of PHF20 protein was significantly higher in glioma cell lines (A172, LN229, U251, HS683 and U87) than that in human astrocyte cell line HEB (p < 0.05)." (PMID 29033691, 2017). "We first examined the expression of PHF20 in various glioma cell lines." (PMID 29033691, 2017). "Moreover, accumulating evidences suggested that PHF20 was expressed in a number of tumors, including glioma, lung cancer and myeloid malignancies." (PMID 29033691, 2017). "Thus, PHF20 might be a novel biomarker for early diagnosis and therapeutic target for treatment of glioma." (PMID 29033691, 2017). "Thus, PHF20 may influence glioma progression by altering these biological processes." (PMID 29033691, 2017). "Interestingly, glioma patients with PHF20 autoantibody have significantly better prognosis than patients without this autoantibody, indicating that a potential therapeutic option for the treatment of GBM is to develop immunotherapy or targeting therapy against PHF20." (PMID 33117706, 2020).
lung carcinoma (5 papers, 2008 to 2022). "Further, PHF20 has been found to be highly expressed in lung cancer, malignant adenoma, brain glioma, and other tumor tissues, and is closely related to the development and progression of tumors." (PMID 33117706, 2020).
breast carcinoma (3 papers, 2017 to 2019). "More recently, G9a was found to methylate ER, a signal recognized by PHF20/MOF histone acetyltransferase complex to result in activation marks at ER-target genes in breast cancer cells." (PMID 30867409, 2019). "Taken together, our data suggest that inhibition of PHF20 by an increase in degradation mediates the effect of JMJD3 on Oct4 expression in breast cancer cells." (PMID 28423536, 2017). "Taken together, JMJD3 inhibits the stem cell-like characteristics in breast cancer by suppression of stemness factor Oct4 in a PHF20-dependent manner." (PMID 28423536, 2017). "Among 11 most commonly amplified/overexpressed PHF genes, we found that three genes, ZMYND8, PHF20, and DIDO1, were significantly highly expressed in advanced-stage breast cancers (T-test: Stage I+II vs III+IV; p < 0.05)." (PMID 28055972, 2017). "Our data showed that upregulation or knockdown of JMJD3 in breast cancer cells decreased or increased the protein level of PHF20, respectively, but did not change the mRNA expression level of PHF20." (PMID 28423536, 2017). "We found that ZMYND8 and PHF20, but not DIDO1, also had significantly higher expression in advanced stages of Luminal breast cancers (p < 0.05)." (PMID 28055972, 2017).
colon cancer (2 papers, 2020 to 2022). "To assess the effect of ALKBH5 on PHF20 mRNA stability, we treated colon cancer cells with actinomycin D and found that ALKBH5 loss improved stability of PHF20 mRNA and prolonged its half‐life." (PMID 35979628, 2022). "Then we carried out rescue experiments to determine whether ALKBH5 had an effect on the biological function of colon cancer cells by regulating PHF20." (PMID 35979628, 2022). "Moreover, our rescue experiments suggested that the knock‐down of PHF20 inhibited the shALKBH5‐mediated enhancement of colon cancer cellular functions in vitro." (PMID 35979628, 2022).
neuroblastoma (2 papers, 2020 to 2025). Neuroblastoma (NB) is the most common solid, extracranial childhood tumor. "Focusing on POU5F1 regulation, it has been shown that PARP1 directly binds to the epigenetic factor PHF20 at the promoter region of POU5F1, activating its transcription in neuroblastoma cells." (PMID 40986050, 2025). "Our previous study demonstrated that PHF20 interacts with WDR5 and plays an important role in cellular reprogramming and neuroblastoma aggressiveness." (PMID 33117706, 2020).
carcinoma of the head and neck (1 paper, 2012). "The genes in the signature, LDLRAP1, PHF20, and LUC7L3, are known to be involved in carcinoma of the head and neck, tumour-associated antigens, and/or cellular signalling." (PMID 22986368, 2012).
developmental delay (1 paper, 2025). "In this study, we report two seemingly unrelated individuals with developmental delay, microcephaly, and distinctive facial features, who harbored a homozygous deletion encompassing PHF20." (PMID 41438488, 2025). "We report two unrelated individuals with developmental delay, microcephaly, and distinctive facial features, in whom exome sequencing and chromosomal microarray analysis revealed a homozygous deletion of PHF20 that segregated with the disease phenotype in their families." (PMID 41438488, 2025).
hypopharyngeal carcinoma (1 paper, 2023). Carcinoma, predominantly squamous cell, arising from the epithelial cells of the hypopharynx. "However, only four genes have been reported to inhibit the chemosensitivity in HSCC or hypopharyngeal carcinoma, including PTGS2, PHF20, ABCC1, and MCL1." (PMID 37791141, 2023).
lung adenocarcinoma (1 paper, 2019). A carcinoma that arises from the lung and is characterized by the presence of malignant glandular epithelial cells. "Knockdown of PHF20 in human lung adenocarcinoma cells leads to reduced cell proliferation as well as diminished H4K16ac 57, suggesting that the MOF‐NSL complex is recruited by PHF20 to H3K4me2‐positive promoters where it catalyzes H4K16ac." (PMID 31267707, 2019). "Indeed, Klein and co‐workers found reduced H4K16ac at PHF20 target genes upon PHF20 knockdown in H1792 lung adenocarcinoma cells." (PMID 31267707, 2019).
Neurodevelopmental delay (1 paper, 2025). "In conclusion, we present preliminary evidence that biallelic loss of PHF20 leads to syndromic neurodevelopmental delay, possibly through dysregulation of acetylation and transcription of genes involved in cell projection and neuron development." (PMID 41438488, 2025).
tumor (13 papers, 2008 to 2026). "Here, we observe a positive correlation between PHF20 expression and the malignancy and tumor grade of cSCC." (PMID 42215448, 2026). "These in vitro findings were corroborated in vivo, where PHF20 knockdown suppressed tumor growth and increased DNA damage." (PMID 42215448, 2026). "KDMC5 and PHF20 are both involved in chromatin remodeling and transcriptomic regulation, while NIT1 is associated to tumor suppressor functions." (PMID 38501112, 2024). "To study the mechanisms by which PHF20 promotes tumor growth and identify the critical downstream factors regulated by PHF20, we performed RNA-sequencing using PHF20 KO, PHF20-Teton, and control cells." (PMID 33117706, 2020). "In recent years, a growing number of studies have shown that PHF20 is closely related to the development of various tumors and plays important roles in tumor suppression and progression." (PMID 29033691, 2017). "Moreover, visualization analysis showed that compared to normal tissues, the m6A peaks of PHF20 mRNA were more abundant in tumour tissues." (PMID 35979628, 2022). "The ablation of PHF20 remarkably reduced the tumor volume and weight." (PMID 33117706, 2020). "Notably, PHF20 was originally found to be a tumor-specific antigen in GBM." (PMID 37090987, 2023). "Notably, PHF20 was initially discovered as a tumor specific antigen in GBM." (PMID 30619286, 2018). "The tumor and development-process marker genes LEF1 and PHF20 have a tendency to change depending on storage time, which will affect the accuracy of correct tumor-marker screening or early screening." (PMID 38674435, 2024). "Subsequently, PHF20 was found abundantly expressed in neurogenic tumors and plays a vital role in carcinogenesis by significantly up-regulating the expression of SOX2 and OCT4, further enhancing the self-renewal and tumor-initiating capability of neuroblastoma." (PMID 30619286, 2018).
cancer (9 papers, 2014 to 2023). A tumor composed of atypical neoplastic, often pleomorphic cells that invade other tissues. "The three transcription factors SFPQ, ZNF639 (also known as ZASC1) and PHF20 have been associated with cancer." (PMID 25089626, 2014). "PHF20 functions as a key epigenetic regulator of stem cell self-renewal and cellular reprogramming, and is abundantly expressed in several cancers." (PMID 33117706, 2020). "Similar to the process of iPSCs induction, our study also shows that PHF20 is indispensable for activation of the OCT4 gene in cancer cells." (PMID 28423536, 2017). "The MAPK signaling pathway included 7 up-regulated and 8 down-regulated genes while pathways in cancer contained 13 up-regulated and 20 down-regulated PHF20-regulated DEGs." (PMID 29033691, 2017). "PHF20 is overexpressed in various cancer tissues compared to adjunct normal tissues, including advanced small-cell lung cancers and advanced adenocarcinomas." (PMID 29033691, 2017). "PHF20 was first identified as an antigen in glioblastoma patients and is highly expressed in different tumors, with potential roles in the development and progression of different cancers, such as glioma, adenocarcinomas, and lung cancer." (PMID 35033534, 2022). "As such, we determined to examine the contribution of PHF20 to cancer stem-like properties." (PMID 33117706, 2020). "Therefore, further in-depth investigations are essential for better understanding of the biological roles of PHF20 in cancer." (PMID 29033691, 2017).
neurological disorders (1 paper, 2017). "In this cohort, seven genes have already been associated with neurological disorders (MNX1, NINJ1, PER2, PHF20, PRSS56, RPH3A, and SBF1) in MalaCards and OMIM." (PMID 28769055, 2017).
PHF20 also shares sentences with these, for which no sentence is quoted: bladder cancer (1 paper); brain glioma (1); cervical cancer (1); colorectal cancer (1); cutaneous squamous cell carcinoma (1); immune diseases (1); microcephaly (1); nasopharyngeal carcinoma (1); neurodevelopmental disorder (1); osteoporosis (1); prostate carcinoma (1); thyroid cancer (1).